PON2 (paraoxonase 2)
Diseases named in the same sentence as PON2 in open-access papers (continued):
Sharing a sentence is not in itself a finding about the gene and the disease.
cancer (34 papers, 2007 to 2025). A tumor composed of atypical neoplastic, often pleomorphic cells that invade other tissues. "Survival analyses have demonstrated that higher PON2 levels are linked to significantly reduced patient survival, while silencing PON2 inhibits cancer cell migration, proliferation, and metastatic potential." (PMID 40794328, 2025). "Together, these studies highlight multiple roles and regulatory pathways of PON2 in cancer, emphasising the protein's potential as a diagnostic and therapeutic target." (PMID 40794328, 2025). "Although initial research on PON2 primarily focused on its antioxidant protective roles in atherosclerosis, recent studies have increasingly implicated it in cancer pathogenesis." (PMID 40794328, 2025). "Overall, these research findings highlight PON2's complex function in managing cancer cell apoptosis and underline its potential as a therapeutic target for improving cancer cell's sensitivity to treatment-induced apoptosis." (PMID 40794328, 2025). "Elevated PON2 levels are associated with aggressive cancer phenotypes, poor prognosis, and resistance to chemotherapy." (PMID 40794328, 2025). "Whatever the cause, based on our in vivo model, we can conclude that decreased expression of PON2 in late stages would be associated with cancer progression." (PMID 29531225, 2018). "In cancer, PON2 and PON3′s association is based on their up-regulated expressions in various tumors with anti-apoptotic and protective effects in the mitochondria from several chemical-mediated dysfunctions." (PMID 28467805, 2017). "Structure-guided drug design may help identify compounds that specifically target cancer-associated PON2 overexpression while sparing its protective antioxidant functions in healthy cells." (PMID 40794328, 2025). "PON2 also impacts apoptosis and its associated mechanisms in multiple forms of cancer." (PMID 40794328, 2025). "The aim of our study was to find PON2 partner proteins, the identification of which will expand our understanding of the functional significance of this protein and possibly reveal new intracellular signaling pathways underlying pathophysiological processes in cancer." (PMID 36653584, 2023). "Following the removal of duplicates, 305 studies were ruled out as they were not relevant to the scope of this review, including those unrelated to PON2, cancer models, or therapeutic/biomarker contexts." (PMID 40794328, 2025). "Using CDDP and other medications, successfully silenced the PON2 gene in several kinds of cancer cell lines, resulting in notable drops in PON2 mRNA and protein levels." (PMID 40794328, 2025). "Overexpression of PON2 protects cancer cells from oxidative damage by ROS, enhancing mitochondrial electron transport chain function and preventing lipid peroxidation." (PMID 40794328, 2025). "PON2 is a multifaceted enzyme with significant roles in cancer biology, spanning proliferation, oxidative stress regulation, and apoptosis." (PMID 40794328, 2025). "Advanced analytical techniques, including Western blotting, immunoprecipitation, and surface plasmon resonance, have further elucidated PON2’s antioxidant activity in cancer cells." (PMID 40794328, 2025). "This narrative review provides a comprehensive evaluation of the roles of paraoxonase 2 in cancer, with a focus on its regulatory mechanisms and potential utility as a biomarker for targeted therapeutic interventions." (PMID 40794328, 2025). "All these data suggest that PON2 represents a promising therapeutic target for treatment of some types of cancer." (PMID 41303537, 2025). "Future research should focus on elucidating the molecular mechanisms regulating PON2 and exploring its potential as a target for the development of effective cancer therapies." (PMID 40794328, 2025). "PON2 regulates essential features of the cancer cell lifecycle, such as invasion, migration, and proliferation." (PMID 40794328, 2025).
cancer (continued). "The overexpression of PON2 has been reported in various cancers, where it contributes to cell survival, chemoresistance, and anti-apoptotic mechanisms." (PMID 40864763, 2025). "Collectively, these studies have explored the regulatory role of PON2 in carcinogenesis, particularly highlighting its potent antioxidative capacity and its involvement in mechanisms that promote cancer cell survival." (PMID 40794328, 2025). "Consistent reductions in proliferation and improved chemotherapeutic sensitivity have been reported in multiple cancer models following PON2 silencing." (PMID 40794328, 2025). "This narrative review aims to elucidate PON2’s enzymatic characteristics and explore its potential modulation as an innovative therapeutic avenue for combating cancer." (PMID 40794328, 2025). "There remain several limitations to the narrative review investigating PON2 as a cancer biomarker and therapeutic target." (PMID 40794328, 2025). "The antioxidant attributes of PON2 play a critical role in helping cancer cells combat chemotherapy by allowing them to sustain oxidative stress." (PMID 40794328, 2025). "A growing body of evidence highlights its dynamic regulation across various cancer models, where PON2 acts as a key modulator of proliferation, redox balance, and apoptosis." (PMID 40794328, 2025). "Continued mechanistic and translational research will be essential to harness the potential of PON2 in cancer diagnostics and treatment strategies." (PMID 40794328, 2025). "PON2 has been shown to lower the production of ROS within mitochondria and shield cell membranes against oxidative damage in various cancer cell lines." (PMID 40794328, 2025). "This narrative review aims to comprehensively synthesize existing literature on PON2 regulation in cancer, enhancing understanding of its multifaceted role and exploring its potential as a prognostic marker and therapeutic target." (PMID 40794328, 2025). "By supporting cellular proliferation, survival, and therapy resistance, PON2 acts as a critical regulator of cancer cell fitness, effects that are markedly diminished upon PON2 knockdown." (PMID 41303537, 2025). "Through its regulatory expression, PON2 effectively circumvents both oxidative stress and pro-apoptotic pathways, thereby facilitating cancer cell survival, as discussed in detail in the following sections." (PMID 40794328, 2025). "Future research on PON2 should focus on elucidating the upstream regulatory pathways and molecular mechanisms that control its expression and activity across different cancer types." (PMID 40794328, 2025). "While PON2 protects cancer cells from oxidative stress, certain conditions (e.g., exposure to C12 or organophosphates) can redirect its function towards pro-apoptotic pathways." (PMID 40794328, 2025). "All of this evidence clearly demonstrates the enzyme’s ability to confer an adaptive advantage on PDAC cells, as well as how different aspects of cancer cell aggressiveness are impacted by PON2." (PMID 38397445, 2024). "A limited but growing number of studies have also demonstrated that PON2 expression negatively correlates with cancer patient prognoses." (PMID 37337025, 2023). "Clearly, there is a discrepancy between PON2’s roles in cancer cell proliferation in vitro and lung tumor progression in vivo." (PMID 37337025, 2023). "In GC cell lines, short interfering RNA (siRNA)-mediated PON2 silencing was achieved, and effect induced on cancer cell phenotype was explored." (PMID 36613780, 2022). "Preliminary and ongoing analyses, performed on a large cohort of matched cancer and normal tissue specimens and aimed to evaluate the prognostic potential of PON2 in OSCC, revealed a significant enzyme dysregulation." (PMID 36613780, 2022). "On the contrary, only recent discoveries illustrated PON2 capacity to modulate the programmed cell death in cancer, by negatively influencing the activation of intrinsic apoptotic pathway." (PMID 36613780, 2022).
cancer (continued). "There is a growing scientific consensus that recognizes a possible role of PON2 in the physiopathology of cancer." (PMID 32093309, 2020). "Our results are consistent with data presented in the literature coming from other studies which have investigated the involvement of PON2 in cancer." (PMID 32093309, 2020). "As reported in the literature, these results confirmed that PON2 is involved in the survival and proliferation of cancer cells." (PMID 32093309, 2020). "In fact, several studies have reported the upregulation of PON2 in different human cancers, including BC." (PMID 32093309, 2020). "We next examined the effect of endogenous PON2 inhibition on IGF-1 expression in human cancer cell lines including ovary (SKOV3), cervical (HeLa), and lung (A549)." (PMID 29531225, 2018). "Next, we investigated the intracellular localization of PON2 inmultiple cancer cell lines and identified the proteins interacting with PON2using the LC-MS/MS technique." (PMID 30397533, 2018). "Using various cancer cell line models, it has been shown that overexpression of PON2 protects from cell death by reducing mitochondrial superoxide levels." (PMID 29531225, 2018). "In conclusion, although further studies are necessary to clarify the role of PON2 in BC cancer cell, our results suggest that the overexpression of this enzyme has an impact on BC cell proliferation and resistance to oxidative stress." (PMID 28430636, 2017). "We observed that GBM cells expressed a higher PON2 protein level compared with normal brain tissue, providing additional support for the importance of PON2 for cancer cell survival." (PMID 28108734, 2017). "The higher expression of PON2 in BC tissues is in agreement with previous studies that reported upregulation of PON2 in few types of human cancers." (PMID 28430636, 2017). "Our results suggest that VPA reduces PON2 expression in GBM cells, which in turn increases ROS production and induces Bim production that inhibits cancer progression via the PON2–Bim cascade." (PMID 28108734, 2017). "The mechanistic insight in this study provides evidence, for the first time, that PON2 expression in human tumors and cancer cell lines is, at least in part, mediated by the Wnt / GSK-3β / β-catenin pathway." (PMID 27322774, 2016). "Taking all this into account and with special regard to aberrant Wnt signaling in cancer, we supposed a regulation of the anti-apoptotic protein PON2 through Wnt signaling in two different cancer sites, which was confirmed in the current study." (PMID 27322774, 2016). "More importantly, the study revealed the fundamental finding of an overall Wnt/GSK3β/β-catenin dependent regulation of PON2 in different cancers, which was confirmed by systematic and multimethodological approaches." (PMID 27322774, 2016). "This enforced us to investigate the impact of the anti-apoptotic protein Paraoxonase-2 (PON2) on cancer and its possible regulation through Wnt signaling." (PMID 27322774, 2016). "This suggests that targeting PON2, possibly through the induction of ROS overload, could sensitize resistant cancer cells and enhance the efficacy of existing chemotherapies." (PMID 40794328, 2025). "Together, these findings underscore the multifaceted role of PON2 in maintaining systemic homeostasis and preventing the onset or progression of various pathologies, including cardiovascular disease, metabolic dysfunction, neurodegeneration and cancer." (PMID 41303537, 2025). "Silencing PON2 sensitizes cancer cells to chemotherapy and inhibits invasion and migration." (PMID 40864763, 2025). "Furthermore, PON2 knockdown was observed to restrict the viability, migration, and invasion of GC cells, outlining its function in the advancement of cancer." (PMID 40794328, 2025). "Identifying lesions at high risk of progression remains a critical goal, and, in the future, enzymes such as NNMT and PON2 may also serve as potential targets for molecular-based cancer therapies." (PMID 40941017, 2025).
cancer (continued). "Some markers were omitted for clarity, although they may also be important, such as the enzyme paraoxonase-2, which detoxifies ROS and is upregulated in many cancers." (PMID 41008989, 2025). "PON2 overexpression protects cancer cells from ROS-induced apoptotic cell death." (PMID 41303537, 2025). "PON2 could serve as an informative biomarker and/or a potential drug target considering its crucial role in regulating cancer cell behaviour in various cancer cell lines and models." (PMID 40794328, 2025). "In addition to apoptosis and bioenergetics, which were first identified as molecular and biochemical aspects potentially regulated by PON2 overexpression, further cellular pathways were discovered to be affected by enzyme dysregulation featuring cancer cells." (PMID 38397445, 2024). "Considering the anti-apoptotic effect exerted by PON2, it is reasonable to expect that modulating enzyme expression could greatly influence the response of cancer cells to conventional CDDP-based treatment based on the drug’s mechanism of action." (PMID 38397445, 2024). "Based on these findings, compounds that inhibit PON2 enzyme activity could be designed, synthesized, and assayed in order to explore their potential use as novel and promising anti-cancer therapeutic agents." (PMID 38397445, 2024). "As concerns the mechanisms potentially involved in CSE-induced ROS production and PON2 regulation in cancer cells, the literature data suggest that, although polyphenols are widely studied for their antioxidant properties in vitro, certain molecules can exert a pro-oxidant effect." (PMID 36235028, 2022). "For example, the overexpression of PON2 in most experimental systems led to cancer promotion." (PMID 36552527, 2022). "The differences in the effects of CSE on PON2 expression in T24 cancer cells and UROtsa could be related to different mechanisms, including intracellular localization of the enzyme and intracellular oxidative balance." (PMID 36235028, 2022). "In addition to apoptosis, other pathways or cellular processes featuring cancer cell started to be explored, in order to discover PON2 potential involvement." (PMID 36613780, 2022). "Therefore, in the present study we investigated the effect of CSE on cell proliferation, intracellular ROS levels, and PON2 expression in normal and cancer cells." (PMID 36235028, 2022). "Over the past years, many studies have described the involvement of PON2 in cancer." (PMID 32093309, 2020). "Theoretically, PON2 should be downregulated in cancers exposed to anoxia." (PMID 32802843, 2020). "VPA appears to increase ROS production via the PON2–Bim cascade, leading to cancer cell death." (PMID 28108734, 2017). "Therefore, several lines of evidence support a role of PON2 in cancer cell death resistance and a regulation through β-catenin." (PMID 27322774, 2016). "Finally, we believe that the hereby enlightened regulation of the anti-apoptotic PON2 through Wnt/β-cat in cancer justifies the need for further studies and can help to develop new therapeutic strategies in anticancer therapy." (PMID 27322774, 2016). "PON2 overexpression raised cancer cell resistance against cytotoxic stimuli, incl." (PMID 27322774, 2016). "Prior studies have shown that the anti-apoptotic and anti-oxidative enzyme PON2 plays a crucial role in cancer cell survival and that some cancer cells up-regulated PON2 expression by yet unknown mechanisms to benefit from its cytoprotective effect." (PMID 27322774, 2016). "PON2 has been shown to be overexpressed in several cancers and it has been suggested that this may be due to the fact that PON2 confers resistance to apoptosis as well as oxidative stress." (PMID 24816800, 2014). "The urokinase plasminogen activator (uPA) system may also be relevant, as this is increased in numerous cancers and upregulates PON2." (PMID 22666600, 2012).
cancer (continued). "Thus, if a cancer cell needs to escape from mitochondrial redox-dependent cell death, it appears beneficial to increase PON2 or PON3 expression." (PMID 22666600, 2012). "Importantly, PON2 appears to contribute to cancer stem cell (CSC) biology." (PMID 40794328, 2025). "Therefore, overproduction of ROS suggests a higher dependence of cancer cells on the antioxidant system to maintain redox balance, which could explain differences in relative PON2 expression among T24 and UROtsa cells." (PMID 36235028, 2022). "Moreover, upregulation of the expression of the enzyme PON2 was observed in cancer cells." (PMID 36235028, 2022). "In this light, PON2 activity, interacting with coenzyme Q10 and lowering of O2− production, leads to the reduction of both cardiolipin peroxidation and cytochrome C release, thus significantly contributing to cancer cell resistance to apoptosis triggered by oxidative stress." (PMID 33297311, 2020). "Moreover, PON-2 located in the nuclear envelope and endoplasmic reticulum, could protect cancer cells against unfavorable environmental conditions and against chemotherapy." (PMID 31052559, 2019). "Therefore, our results support the hypothesis that PON2 upregulation observed in BC tissues could represent an adaptive mechanism, which could enable the cancer cells to escape cell death and apoptosis." (PMID 28430636, 2017). "The PON family of enzymes, comprising PON1, PON2, and PON3, are highly expressed in various cancer cells and play critical roles in promoting cell survival and metastasis." (PMID 40794328, 2025). "rupestris (CSE) on cell proliferation, intracellular ROS levels, and expression of the antioxidant and anti-apoptotic enzyme paraoxonase-2 (PON2) in normal and cancer cells." (PMID 36235028, 2022). "In conclusion, our data demonstrate that normal and cancer cells are differentially sensitive to CSE, which has different effects on PON2 gene expression as well." (PMID 36235028, 2022). "It has been reported that PON2 and PON3 are upregulated in various cancer tissues including ovarian cancer." (PMID 29531225, 2018). "PON2 lowers the stress-induced pro-apoptotic protein CHOP, which contributes to the development of chemotherapeutic resistance in cancer cells." (PMID 26009874, 2015). "In the following section, we give an overview of studies that assessed expression of PON1, PON2, or PON3 in various cancers, with the majority of studies seemingly reporting a deregulation of these proteins." (PMID 22666600, 2012). "We will focus on the role of PON2 and PON3 in cancer based on recent discoveries on the mechanism of action of these proteins in proliferation and apoptosis." (PMID 22666600, 2012). "Using the same cDNA arrays as for PON2, our group showed a considerably increased PON3 expression in all tested cancer types, except cervix." (PMID 22666600, 2012). "Mechanisms by which PON2 contributes to resistance to cancer chemotherapy drugs have not yet been elucidated." (PMID 38434765, 2024). "The results indicated that the expression level of PON2 was increased in cancer cells, indicating a negative correlation between miR-376a-3p and PON2 expression." (PMID 33600548, 2021). "In general, high PON2 levels in many cancers is a negative factor that decreases patient survival." (PMID 36653584, 2023). "Assessment of PON2 protein levels is not feasible in hundreds of cancer samples." (PMID 22666600, 2012). "However, the role and mechanism of action of PON2 in cancer has not been elucidated." (PMID 29531225, 2018).